Y_RNA (Y RNA )
Gene: Miscellaneous RNA gene on chromosome 10 (17,403,508 to 17,403,620, forward strand). Ensembl gene ENSG00000251803.
Homologues: Orthologues: chimpanzee Y_RNA (99% identical), guinea pig Y_RNA (88% identical), guinea pig Y_RNA (83% identical). Paralogues in human: RNY1 (88% identical), Y_RNA (88% identical), Y_RNA (86% identical), Y_RNA (85% identical), Y_RNA (84% identical), RNY1P11 (83% identical), Y_RNA (83% identical), Y_RNA (82% identical), RNY1P8 (81% identical), Y_RNA (81% identical), RNY1P12 (80% identical), RNY1P2 (80% identical), and 96 more.